METTL14 (methyltransferase 14, N6-adenosine-methyltransferase non-catalytic subunit)
Diseases named in the same sentence as METTL14 in open-access papers (continued):
Sharing a sentence is not in itself a finding about the gene and the disease.
esophageal cancer (9 papers, 2021 to 2025). A primary or metastatic malignant neoplasm involving the esophagus. "Exosomal miR-130a-3p confers cisplatin resistance in esophageal cancer by regulating ferroptosis through m6A RNA methylation of FSP1 mediated by METTL14." (PMID 41361055, 2025). "In our current study, employing a pan-cancer analytical approach, we developed METTL3 and METTL14 knockdown EC109 esophageal cancer cell lines to explore the impact of gene silencing on cellular proliferation." (PMID 38965238, 2024). "We found that HNRNPC, YTHDF, ZC3H13, YTHDC2, and METTL14 were dysregulated in esophageal cancer tissues." (PMID 34395102, 2021). "From the TCGA database, we found that several m6A-associated genes, including YTHDF1, HNRNPC, ZC3H13, YTHDC2, and METTL14 were dysregulated in esophageal cancer compared to matched normal tissues." (PMID 34395102, 2021). "Moreover, we found that the m6A methyltransferase METTL14 negatively regulates FTO function in esophageal cancer progression." (PMID 38491196, 2024). "Notably, the METTL14/FTO/AKT3 signaling network might have other normal functions in addition to influencing tumorigenesis in esophageal cancer." (PMID 38491196, 2024). "We found that the m6A methyltransferase METTL14 is also involved in FTO-regulated m6A modification and acts in concert with FTO to regulate AKT3 methylation in the tumorigenesis and metastasis of esophageal cancer." (PMID 38491196, 2024). "The methyltransferase-like 14 (METTL14) promotes cancer stem cell persistence and mediates radioresistance in esophageal cancer." (PMID 38970106, 2024). "Based on these results, we investigated the correlation between the combined effect of FTO and multiple m6A regulatory proteins and the prognosis of esophageal cancer patients and found that an increase in the FTO/METTL14 ratio can lead to poor prognosis." (PMID 38491196, 2024). "In contrast, METTL14 knockdown had the opposite effect: METTL14 knockdown increased the migration or invasion of KYSE150 cells, but the effects of METTL14 on esophageal cancer cell phenotype induced by FTO between the two." (PMID 38491196, 2024). "Then, ELISA result showed that METTL3 and METTL14 were highly expressed in esophageal cancer, whereas FTO and ALKBH5 expressed lowly in esophageal cancer." (PMID 33596916, 2021). "Moreover, we found that the m6A methyltransferase METTL14 is also involved in FTO-regulated m6A modification and acts in concert with FTO to regulate AKT3 methylation in the tumorigenesis and metastasis of esophageal cancer." (PMID 38491196, 2024). "However, during the development of esophageal cancer, FTO has an antagonistic effect on the expression of METTL14, and this effect is related to the ratio of FTO to ALKBH5." (PMID 38491196, 2024). "Importantly, we revealed that FTO operates through a regulatory network of m6A modifications that involves METTL14, YTHDF1 and AKT3 signaling, providing the first insight into the mechanism of FTO-mediated esophageal cancer progression." (PMID 38491196, 2024). "FTO alone is not related to the prognosis of esophageal cancer, and its function is antagonized by METTL14." (PMID 38491196, 2024). "Furthermore, our study indicated that although METTL3, METTL14, FTO and ALKHB5 differentially expressed in esophageal cancer patients’ tissues and normal esophageal tissues, only METTL3 expression was related to esophageal cancer recurrence." (PMID 33596916, 2021). "We found that downregulation of FTO or overexpression of METTL14 had similar effects on multiple aspects of esophageal cancer progression, including migration, invasion, proliferation, and tumorigenesis, which also suggested that FTO function could be restored by METTL14 in esophageal cancer." (PMID 38491196, 2024).
esophageal squamous cell carcinoma (9 papers, 2022 to 2025). Esophageal squamous cell carcinoma (ESCC) is a type of esophageal carcinoma (EC) that can affect any part of the esophagus, but is usually located in the upper or middle third. "Additionally, decreased METTL14 has been reported to promote radiotherapy resistance in esophageal squamous cell carcinoma (ESCC) and sorafenib resistance in HCC." (PMID 39098905, 2024). "Similarly, CSCs generation and radiosensitivity in esophageal squamous cell carcinoma (ESCC) were also influenced by m6A methyltransferase METTL14." (PMID 35843942, 2022). "For instance, in esophageal squamous cell carcinoma (ESCC), METTL14 upregulates miR-99a-5p by modulating the processing of m6A-mediated DGCR8-dependent pri-miR-99a." (PMID 40161350, 2025). "A pan-cancer analysis leveraging The Cancer Genome Atlas (TCGA) data has identified pronounced disparities in the expression patterns, functional roles, and correlations with tumor burden between METTL3 and METTL14, particularly in esophageal squamous cell carcinoma (ESCC)." (PMID 38965238, 2024). "Similarly, METTL14 was shown to enhance the expression of miR-99a-5p, which inhibits the persistence of cancer stem-like cells (CSCs) and reduces the radioresistance of esophageal squamous cell carcinoma (ESCC)." (PMID 41369374, 2025). "However, in our study, with EC109 esophageal squamous cell carcinoma cells, we found significant differences in the binding partners of METTL3 and METTL14." (PMID 38965238, 2024). "In esophageal squamous cell carcinoma (ESCC), ZC3H13 modulates METTL14/METTL3 nuclear transport and stabilizes CXCL8 mRNA, driving M2 polarization and infiltration, thereby facilitating immune evasion." (PMID 41164187, 2025). "Liu and his team identified a crucial regulatory METTL14-miR99a-5p-TRIB2 feedback circuit that promoted cancer stemness and radioresistance in esophageal squamous cell carcinoma (ESCC)." (PMID 36517820, 2022). "Similarly, in esophageal squamous cell carcinoma (ESCC), METTL3 and METTL14 demonstrate distinct functional roles." (PMID 38965238, 2024).
renal carcinoma (8 papers, 2020 to 2025). A carcinoma arising from the epithelium of the renal parenchyma or the renal pelvis. "Notably, in renal cancer, METTL14 suppresses the migration and invasion capabilities of renal cancer cells through m6A modification." (PMID 38664644, 2024). "In renal carcinoma, METTL14 was down-regulated and abrogated P2RX6 expression via m6A modification to suppress renal cancer cell migration and invasion." (PMID 34503454, 2021). "A recent study reported that METTL14 could mediate P2RX6 mRNA and protein level, promoting renal cancer cells migration and invasion via ATP-induced Ca2+ influx modulating ERK1/2 phosphorylation and MMP9 signal pathway in vitro and in vivo assays." (PMID 32038982, 2020).
Sepsis (8 papers, 2020 to 2025). Sepsis is defined as life-threatening organ dysfunction caused by a dysregulated host response to infection. "We observed substantial heterogeneity in the expression of demethylases (ALKBH5, FTO) and methyltransferase complex components (WTAP, METTL3, METTL14), suggesting their potential involvement in the epigenetic regulation of immune function during sepsis." (PMID 40625751, 2025). "In the present study, we found that METTL14 knockdown alleviated lung injury via inhibiting NLRP3 inflammasome activation in macrophages, consistent with the result in sepsis-associated myocardial dysfunction." (PMID 38218935, 2024). "Further data have demonstrated that METTL14-mediated m6A methylation negatively regulates inflammatory response in the context of sepsis." (PMID 38112620, 2023). "It is understood that SOCS1 and Spi2a mRNA stability as well as translation are improved by METTL14-YTHDF1-dependent m6A methylation to prevent the progression of sepsis." (PMID 38112620, 2023). "Therefore, METTL3 and METTL14 worked in a protective role to maintain microvascular circulation and myocardial function during sepsis." (PMID 34869371, 2021). "VEGF has also been reported to be increased in response to septic inflammation, which provides a reasonable explanation for the regulation of METTL3, METTL14, and IGF2BP3 in sepsis." (PMID 34869371, 2021). "Using qRT-PCR, we detected that the expression of METTL3 and WTAP in the aorta was significantly downregulated during sepsis, while that of YTHDF 1, YTHDF 3, METTL14, and FTO did not change significantly." (PMID 34507301, 2021).
diabetic nephropathy (7 papers, 2021 to 2025). "METTL14 orchestrates fibrosis through divergent mechanisms: MAPK/ERK activation via TUG1 regulation in diabetic kidney disease, Sirt1 suppression in focal segmental glomerulosclerosis, and BPTF-driven glycolytic reprogramming in RCC." (PMID 40895041, 2025). "Our data revealed that METTL14 plays a vital role in high glucose-induced glomerular endothelial cells and diabetic nephropathy through m6A modification of α-klotho." (PMID 34503454, 2021). "Furthermore, METTL14 appears to play a critical role in diabetic nephropathy through the m6A modification of α-klotho." (PMID 40299682, 2025). "Moreover, significantly increased expression levels of METTL14 were observed in the kidneys of mice suffering from diabetic nephropathy." (PMID 39686999, 2024). "In conclusion, our study found that METTL14 could aggravated high glucose-induced glomerular endothelial cell injury and diabetic nephropathy through m6A modification of α-klotho." (PMID 34503454, 2021). "In the current study, we investigated the functions of METTL14 on glomerular endothelial cell injury in vitro and diabetic nephropathy in vivo, and explored whether METTL14 works through mediating m6A modification of α-klotho." (PMID 34503454, 2021). "Interestingly, METTL14 expression is upregulated in renal tissues of diabetic nephropathy patients and in human renal glomerular endothelial cells (HRGECs) exposed to high-glucose conditions, suggesting its critical role in exacerbating renal inflammatory responses and oxidative stress." (PMID 40895041, 2025). "They observed that METTL14 was significantly increased in renal biopsy samples from patients with FSGS and diabetic kidney disease, as well as in cultured human foot cells treated with Adriamycin or AGE in vitro." (PMID 37841018, 2023). "METTL14 was also evidently increased in renal biopsy samples from patients with focal segmental glomerulosclerosis (FSGS) and diabetic nephropathy and in cultured human podocytes with ADR or advanced glycation end product (AGE) treatment in vitro." (PMID 34580283, 2021). "In this study, we observed the elevated m6A RNA levels and the most upregulated METTL14 expression in kidneys of mice with adriamycin (ADR) and diabetic nephropathy." (PMID 34580283, 2021).
neuroblastoma (7 papers, 2021 to 2024). Neuroblastoma (NB) is the most common solid, extracranial childhood tumor. "Recent studies have reported novel associations between the functional SNPs of the METTL14 gene and susceptibility to many human diseases, such as Wilms tumor, neuroblastoma, hepatoblastoma, acute lymphoblastic leukemia, and coronary heart disease." (PMID 39831202, 2024). "Our group first found that some SNPs in the METTL14 gene were closely associated with the risk of neuroblastoma." (PMID 35115038, 2022). "METTL14 gene rs298982 G > A and rs62328061 A > G were significantly associated with reduced susceptibility to neuroblastoma, while rs9884978 G > A and rs4834698 T > C were associated with increased susceptibility to neuroblastoma." (PMID 35115038, 2022). "Together, these results support the potential of METTL3/METTL14 complex inhibition as a therapeutic strategy against neuroblastoma." (PMID 38691450, 2024). "High expression of METTL14 was correlated with low survival of neuroblastoma patients along with reduced expression of WTAP or a high expression of YTHDF1." (PMID 34093133, 2021). "Polymorphisms in METTL14 gene and METTL3 gene (m6A methyltransferases) were also reported to be associated with predisposition to neuroblastoma." (PMID 34897032, 2021). "METTL3 and METTL14 protein levels were analyzed across the 11 human neuroblastoma cell lines." (PMID 38691450, 2024). "However, little is known about the m6A epitranscriptome or the role of the METTL3/METTL14 complex in neuroblastoma, a common pediatric cancer." (PMID 38691450, 2024).
oral squamous cell carcinoma (7 papers, 2021 to 2025). "METTL14 suppresses the development of oral squamous cell carcinoma by activating autophagy via m6A/IGF2BP2-dependent modification on FIP200 stability." (PMID 39897540, 2025). "Downregulation of METTL14 expression correlates with advanced clinicopathological features and poor prognosis of oral squamous cell carcinoma (OSCC)." (PMID 39289775, 2024). "METTL3/ METTL14 upregulation enhanced the resistance of oral squamous cell carcinoma (OSCC) to cisplatin by inhibiting the interleukin -17 (IL-17) signaling." (PMID 36835633, 2023). "Rapamycin-induced autophagy increased m6A RNA methylation via METTL14 in oral squamous cell carcinoma (OSCC) cells." (PMID 36835633, 2023). "METTL14 enhances RB1CC1 expression after transcription in an m6A-IGF2BP2-dependent manner, thereby affecting autophagy and progression of oral squamous cell carcinoma." (PMID 39289775, 2024).
type 2 diabetes (7 papers, 2020 to 2025). "Therefore, the METTL14/METTL3/G6pc mRNA m6A pathway may serve as new therapeutic targets for type 2 diabetes treatment." (PMID 40278833, 2025). "In a recent study, demethylases FTO have been demonstrated to positively correlate with methyltransferases methyltransferase complex (METTL3, METTL14, and WTAP) in patients with type 2 diabetes." (PMID 32583611, 2020). "We postulated that obesogenic factors might upregulate hepatic METTL14 and METTL3 to activate the G6pc mRNA m6A/G6pc synthesis/HGP pathway, thereby exacerbating type 2 diabetes progression." (PMID 40278833, 2025). "METTL14-dependent m6A mRNA methylation regulated human β-cell biology, including cell-cycle progression, insulin secretion, and the Insulin/IGF1-AKT-PDX1 pathway in type 2 diabetes (T2D)." (PMID 37612540, 2023).
Glucose intolerance (6 papers, 2020 to 2025). Glucose intolerance (GI) can be defined as dysglycemia that comprises both prediabetes and diabetes. "METTL14 deficiency has been also demonstrated to decreased insulin secretion and lead to glucose intolerance." (PMID 36891946, 2023). "It is likely that METTL14 overexpression alone is insufficient to induce glucose intolerance and liver steatosis." (PMID 40278833, 2025). "For METTL14, specific knockout of METTL14 in β-cells resulted in reduced insulin secretion and induced glucose intolerance by activating the IRE1α/sXBP-1 pathway." (PMID 35692393, 2022). "In addition, METTL14 is essential for β-survival, differentiation and insulin secretion, the deficiency of METTL14 in β-cells increases cell death, changes cell differentiation and decreases β-cell mass and insulin secretion, leading to glucose intolerance and T2D." (PMID 32110378, 2020).
ischemic stroke (6 papers, 2022 to 2025). A stroke disorder caused by obstruction of blood flow to the brain, due to thrombotic (local blood clot formation) or embolic (due to a blood clot or other material traveling from another site) event. "In a study of carotid atherosclerosis, a common cause of ischemic stroke, Mettl14 increased the m6A methylation of Foxo1 mRNA, which promoted Foxo1 translation and transcription factor activity to increase endothelial inflammation." (PMID 38360659, 2024).
lung adenocarcinoma (6 papers, 2022 to 2025). A carcinoma that arises from the lung and is characterized by the presence of malignant glandular epithelial cells. "Conversely, in lung adenocarcinoma, METTL14 overexpression augments tumor cell proliferation, migration, and invasion, whereas its knockdown exerts the opposite effect." (PMID 40746896, 2025). "Interestingly, METTL14 expression is also significantly increased in lung adenocarcinoma tissues, and METTL14 knockdown markedly reduces cancer cell migration and invasion." (PMID 40986143, 2025). "However, the specific mechanism by which METTL14 regulates glucose-6-phosphate dehydrogenase (G6PD) to promote the progression of lung adenocarcinoma (LUAD) is not well understood." (PMID 39138186, 2024).
viral infections (6 papers, 2019 to 2024). "Together, these data indicate that viral infection induces the upregulation of METTL14 protein-mediated methylation in host cells." (PMID 38551978, 2024). "Previous studies have demonstrated an interaction between DDX5 and METTL3, as well as an interaction between METTL3 and METTL14 to form a m6A writer complex upon virus infection." (PMID 38182816, 2024). "METTL14 collaborates with METTL3 in regulating the replication of various viruses, including HCV, HDV, IAV, HSV-1 and HIV, suggesting a supporting role for METTL14 in these viral infections." (PMID 38551978, 2024). "siRNA knockdown of METTL14 expression in primary peritoneal macrophages also elevated MAVS protein level after virus infection." (PMID 34047074, 2021). "We found SeV infection increased the steady state mRNA level of Ddx58 in both Mettl14+/+ and Mettl14+/− macrophages in a similar kinetics after virus infection." (PMID 34047074, 2021). "Mettl14+/− mice showed improved survival than their WT littermates during viral infection." (PMID 34047074, 2021). "Furthermore, depletion of METTL3 and METTL14 has also been shown to lead to elevated levels of type I interferon responses to myriad viral infections." (PMID 31482095, 2019). "Knockdown of METTL3, METTL14, and YTHDF2 significantly increased viral infection and replication, while knockdown of ALKBH5 decreased viral infection and replication." (PMID 35465335, 2022). "The results showed that the mRNA and protein expressions of METTL14 in lymph node, spleen, and kidney increased upon viral infection, while there were no significant changes in the lung, tonsil, heart, and intestine." (PMID 38551978, 2024). "The steady state mRNA levels of Tbk1 and Irf3 in both Mettl14+/+ and Mettl14+/− macrophages were not changed after virus infection." (PMID 34047074, 2021).
bladder tumor (5 papers, 2019 to 2022). "Recently, a study revealed that the methyltransferase METTL14 downregulation was responsible for the decreased m6A modification in bladder tumor-initiating cells." (PMID 35211409, 2022). "Mettl14 knockout cells have enhanced invasion capacity, revealing the inhibition of Mettl14 in bladder tumor invasion." (PMID 31760940, 2019). "However, it also has been reported that inhibiting METTL14 (methyltransferase-like protein 14)-mediated m6A abundance facilitates the development of bladder tumor-initiating cells (TICs)." (PMID 35090469, 2022). "Differently, the previous study focused on the inhibitory role of METTL14 in BCa tumor initiating capacity of bladder tumor initiating cells, sphere formation, invasion and tumor propagation while ours uncovered its suppression on BCa cell migration, invasion and EMT as well as tumor metastasis." (PMID 36288387, 2022). "However, some m6A regulators, including METTL3, RBM15B, YTHDF1, YTHDF2, and IGFBP3, were significantly overexpressed in bladder tumors, and some m6A regulators, including METTL14, METTL16, ZC3H13, and YTHDF3, were markedly downregulated in bladder tumors." (PMID 35004726, 2021). "Moreover, a positive correlation of Mettl14 expression and m6A content was observed in bladder tumors." (PMID 31760940, 2019). "Interestingly, Mettl14 was also lowly expressed in advanced bladder tumors and related to the prognosis of bladder tumor patients." (PMID 31760940, 2019). "Moreover, a negative correlation of Mettl14 expression and Notch1 expression was observed in bladder tumors." (PMID 31760940, 2019).